PRMT5 (protein arginine methyltransferase 5)
Diseases named in the same sentence as PRMT5 in open-access papers (continued):
Sharing a sentence is not in itself a finding about the gene and the disease.
leukemia (continued). "Recently, DOT1L and PRMT5 have been identified as suitable targets with only minor side effects for the treatment of poor prognosis MLLr leukemia and we could demonstrate that the combination of both resulted in synergistic effects." (PMID 32456310, 2020). "Inhibition of methyltransferase PRMT5 suppresses self-renewal of human leukemia stem cells." (PMID 31537905, 2020). "Importantly, CRISPR-Cas9 screens in MLL-rearranged AML mouse models defined PRMT1 and PRMT5 as essential genes and consequently potential targets in this type of leukemia." (PMID 31552175, 2019). "Overexpression or enhanced activity of PRMTs has been recognized in multiple type of cancers (breast, prostate, lung, colon, leukemias), cardiovascular diseases, but also in neurodegenerative diseases (Huntington’s disease (PRMT5) and Alzheimer disease (PRMT5))." (PMID 30103412, 2018). "Indeed, pre-clinical PRMT5 inhibitors have recently demonstrated impressive efficacy in mouse models of leukaemia." (PMID 29876520, 2018). "Interestingly, forced expression of PRMT5 led to the delayed onset of leukemia in irradiated mice, indicating that PRMT5 may play a tumor suppressor role in Fanconi anemia patients." (PMID 29568320, 2018). "Furthermore, K-rasG12D-induced leukemia was significantly delayed in recipient mice transplanted with Fanca−/− Luc-LSL-K-rasG12D/CreER LSK cells expressing PRMT5 compared with the recipient mice of donor Fanca−/− Luc-LSL-K-rasG12D/CreER LSK cells carrying the vector control virus." (PMID 27507053, 2016). "For example, PRMT5 regulation of POLD1 and ATM via AS have been previously suggested by us and others in leukemias and uveal melanomas." (PMID 37861290, 2023). "The high expression of PRMT1 has been shown to block cell differentiation and propagate leukemia, whereas PRMT4 (CRAM1) and PRMT5 affected RNA splicing in hematological malignancies." (PMID 35565298, 2022). "In leukemia cell lines, the H3R2 and H3R8 symmetrical dimethylation by PRMT5 antagonizes H3K27 trimethylation by PRC2, thus, maintaining the transcription of target genes, resulting in proliferative effects and cell cycle activation." (PMID 36358861, 2022). "In MLLr leukemia, the MAT2A product SAM serves as a substrate for many important methyltransferases like the H3K79 histone methyltransferase DOT1L or PRMT5, both involved in the pathogenesis of the disease." (PMID 32456310, 2020). "PRMT5, a driver oncogene in cooperation with nuclear Cyclin D1T286A is also involved in other driver oncogene pathogenesis in aggressive T-cell lymphoma and leukemia." (PMID 36358861, 2022). "Furthermore, forced expression of PRMT5 in HSPCs from LSL-K-rasG12D/CreER-Fanca−/− mice prolongs oncogenic response and delays leukemia development in recipient mice." (PMID 27507053, 2016). "Furthermore, we found that the co-culture of MTAP-deleted cells with suspended MTAP-WT leukemia cells (MV-4-11, myeloid-like) resulted in higher SDMA levels—indicating higher PRMT5 activity and lower intracellular MTA levels—compared to the monoculture MTAP-deleted cells." (PMID 34244484, 2021).
melanoma (45 papers, 2013 to 2026). A malignant, usually aggressive tumor composed of atypical, neoplastic melanocytes. "We next tested the effects of PRMT5 loss on proliferation and relevant pathways in melanoma cell lines." (PMID 24098663, 2013). "In this study, PRMT5 depletion was associated with decreased MITF in a majority of human melanoma cell lines." (PMID 24098663, 2013). "To determine how PRMT5 loss affects melanoma function, we utilized PRMT5-targeting siRNA." (PMID 24098663, 2013). "Secondly, in melanoma models, knockdown of PRMT5 has been shown to reduce tumor growth in immunocompetent mice, but not in immunodeficient ones." (PMID 40157258, 2025). "Combining PRMT5 inhibitor GSK3326595 with ICB therapy can limit melanoma growth and enhance immunotherapy efficacy in mice." (PMID 39885614, 2025). "It is reported that the melanoma response to antitumor immunity is defined by PRMT5 modulation of the cGAS/STING and NLRC5 pathways." (PMID 40777599, 2025). "PRMT5 was found to specifically downregulate MDM4 protein levels in melanoma cell lines; multiple PRMT5 small molecule inhibitors are currently under evaluation in clinical trials." (PMID 39273363, 2024). "As a primary epigenetic regulator, protein arginine methyltransferase 5 (PRMT5) is involved in various cell growth processes and has been reported to be associated with the development and progression of melanoma." (PMID 37163421, 2023). "Understanding the effects of CDK4/6 inhibition on alternative splicing in melanoma cells and its dependency on PRMT5 is crucial." (PMID 37917641, 2023). "Our findings shed light on the role of PRMT5 in mediating changes to alternative splicing in response to CDK4/6 inhibition in melanoma." (PMID 37917641, 2023). "CHL1 and A375 melanoma cells were subjected to treatment with 500 nM of the PRMT5 inhibitor GSK3326595 for 72 hours or with 1 μM of the CDK4/6 inhibitor palbociclib for either 72 hours or 6 days." (PMID 37917641, 2023). "In this study, treatment of melanoma cells with palbociclib resulted in suppression of PRMT5 activity, which altered pre-mRNA splicing of MDM4 and downregulated MDM4 protein levels." (PMID 37502925, 2023). "Overall, these findings highlight the distinctive effects of CDK4/6 and PRMT5 inhibition on alternative splicing in melanoma cells." (PMID 37917641, 2023). "Studies have shown that, in mouse melanoma, PRMT5 overexpression promotes tumor growth, while deprivation of Prmt5 inhibits tumor growth." (PMID 35531958, 2022). "Treatment of melanoma cells with one of these inhibitors, palbociclib, decreased PRMT5 activity in sensitive cell lines, reducing target protein methylation and inducing the MDM4 AS switch known to be associated with PRMT5 inhibition." (PMID 34065983, 2021). "The methylation of Ser/Tyr RAF1 is also regulated by PRMT5 in melanoma cells, where PRMT5 methylates RAF1 at R563, and downregulates MEK1/2-ERk1/2 protein kinases." (PMID 33670008, 2021). "In melanoma, PRMT5 inhibition has been shown to increase both neoantigen expression via perturbation of alternative splicing and also immunogenicity with increased MHC class I expression through hypomethylation of NLRC5." (PMID 34680285, 2021). "Monotherapy is ineffective; combination of either genetic or pharmacological PRMT5 inhibitors with anti-PD-1 therapy results in the inhibition of melanoma growth, which is CD8 T cell-dependent." (PMID 35111150, 2021). "In melanoma cells it has been demonstrated that in hypoxic conditions, EV exhibit a miRNome and proteome signature (AKR7A2, DDX39B, EIF3C, FARSA, PRMT5, VARS), which is associated with poor prognosis for the patients." (PMID 34439311, 2021). "PRMT5 is overexpressed in many cancers, such as melanoma, lung, and gastric cancers; and overexpression of PRMT5 is usually associated with poor prognosis." (PMID 34124017, 2021).
melanoma (continued). "In this context, PRMT5 control of SKI enhances melanoma growth by upregulating SOX10 and PAX3, which drive melanoma growth." (PMID 32743345, 2020). "Hypoxic melanoma EVs carried a hypoxic signature consisting of six proteins (AKR7A2, DDX39B, EIF3C, FARSA, PRMT5, VARS) which were significantly associated with a poor prognosis for melanoma patients." (PMID 32183388, 2020). "PRMT5 expression has been found to be increased in melanoma, and siRNA-mediated depletion of PRMT5 resulted in a substantial decrease in the level of MITF protein indicating a positive regulatory effect." (PMID 25433395, 2015). "Overall, the number of samples with ≥5% PRMT5+ cells was significantly higher in malignant (121 of 135 samples PRMT5+) and metastatic (58 of 66 samples PRMT5+) melanoma specimens versus normal epidermis (1 of 21 samples PRMT5+; p<0.0001)." (PMID 24098663, 2013). "PRMT5 regulated melanoma cell growth, as siRNA-mediated PRMT5 depletion inhibited proliferation in a subset of metastatic melanoma cell lines (including Hs294T, 1106Mel, WM1366, and CHL-1) but accelerated growth of others (A375, MeWo)." (PMID 24098663, 2013). "Namely, in the prior report, PRMT5 was shown to associate with CRAF in PC12 and Cos7 cells, and modulate ERK signaling in BRAF wild type melanoma cells activated with human growth hormone." (PMID 24098663, 2013). "Immunohistochemical analysis indicated significant upregulation of PRMT5 in human melanocytic nevi, malignant melanomas and metastatic melanomas as compared to normal epidermis." (PMID 24098663, 2013). "Depletion of PRMT5 via siRNA inhibited proliferation in a subset of melanoma cell lines, while it accelerated growth of others." (PMID 24098663, 2013). "Reports also demonstrate that PRMT5 regulates ERK signal transduction amplitude in BRAF wild type melanoma cell lines." (PMID 24098663, 2013). "To date, only one report has published a role for PRMT5 in melanoma, in which PRMT5 was shown to modulate the ERK pathway in BRAF wild type cells." (PMID 24098663, 2013). "A series of studies was conducted in a panel of human metastatic melanoma cell lines to explore the role of PRMT5 in melanoma biology." (PMID 24098663, 2013). "PRMT5 protein expression in human melanoma specimens was evaluated by IHC in 248 de-identified tissues from individual patient samples and two separate tissue microarrays." (PMID 24098663, 2013). "Together these results highlight important factors that deserve consideration, as therapeutic strategies move toward targeting PRMT5 or other methyltransferases in melanoma." (PMID 24098663, 2013). "In melanoma, inhibition of PRMT5 sensitizes melanoma cells to CDK4/6 inhibitor." (PMID 41513606, 2026). "In melanoma, upregulation of PRMT5 inhibits inflammation and antigen presentation." (PMID 39885614, 2025). "PRMT5 was significantly upregulated in melanoma tissues compared to normal skin (P < 0.001)." (PMID 41425556, 2025). "We found that both WDR77 and PRMT5 are upregulated in melanoma." (PMID 41425556, 2025). "Whether PRMT5 inhibition should be used alone or combined with immunotherapy in melanoma patients, particularly those who fail immunotherapy, requires further clinical investigation." (PMID 41425556, 2025). "Therefore, increased interferon and chemokine expression and presentation of antigens via MHC class I upon PRMT5 inhibition sensitizes the investigated melanoma models to immune checkpoint therapy." (PMID 40157258, 2025). "Similarly, metastatic melanomas exhibit reduced nuclear PRMT5 expression compared to primary cutaneous melanomas, with higher cytoplasmic PRMT5 expression observed in melanoma tissue relative to normal skin epidermal cells." (PMID 38791992, 2024). "However, it has been reported that PRMT5 down-regulates cGAS-mediated antiviral immune response or type I IFN response in a melanoma mouse model." (PMID 38838142, 2024). "PRMT5 inhibition antagonizes melanoma growth in immunocompetent mice." (PMID 37163421, 2023).
melanoma (continued). "PRMT5 knockdown melanoma cell xenograft tumor growth was inhibited in immunocompetent C57BL/6 mice." (PMID 36980950, 2023). "Furthermore, the melanoma cell xenografted tumor was shrunk following combination treatment with a PRMT5 inhibitor (GSK3326595) and an anti-PD-1 antibody." (PMID 36980950, 2023). "Knockdown of PRMT5 promoted MHC-I accumulation at the cell surface of melanoma cells." (PMID 33925158, 2021). "Interestingly, the epigenetic modifier Protein arginine methyltransferase 5 (PRMT5) downregulates NLRC5 expression in melanoma cells, leading to a decrease of MHC-I-mediated antigen presentation." (PMID 33925158, 2021). "Recently, PRMT5 was shown to be involved in drug resistance against CDK4/6 inhibitors in melanoma." (PMID 32183388, 2020). "This could be due to the increased expression of PRMT5 in the melanoma hEVs, as PRMT5 well as RNA have recently been shown to regulate cancer cell invasion." (PMID 32183388, 2020). "Indeed, genetic or pharmacologic (GSK3326595) inhibition of PRMT5 sensitizes ICT-unresponsive cold melanoma (B16F10, or YUMM1.7) to anti-PD1 therapy." (PMID 32743345, 2020). "Effects of PRMT5 siRNA on microRNA (miR) expression in human melanoma cell lines." (PMID 24098663, 2013). "Thus, the interactions of PRMT5 with other proteins are likely to be unique in human melanoma cells." (PMID 24098663, 2013). "Our data demonstrated that PRMT5 did not associate with CRAF in unstimulated wild-type or BRAFV600E mutant melanoma cell lines." (PMID 24098663, 2013). "For these reasons, we postulated that PRMT5 deserved further investigation in melanoma." (PMID 24098663, 2013). "Although it was expressed predominantly in the cytoplasm of human melanoma cell lines, clinical and orthotopic tumor data indicate that cellular localization of PRMT5 may be modulated by the tumor microenvironment." (PMID 24098663, 2013). "In conclusion, we demonstrate that PRMT5 is expressed in human melanoma and melanocytic nevi." (PMID 24098663, 2013). "Data from this study indicate that although PRMT5 is expressed at high levels, previously published protein-protein interactions may differ in melanoma when compared to those in other malignancies." (PMID 24098663, 2013). "Together, these studies indicate that PRMT5 may play diverse roles in regulating melanoma cell biology and is prone to influence by exogenous stimuli." (PMID 24098663, 2013). "Ultimately the lack of interaction between PRMT5 and cyclin D1 or STAT3, and differences in subcellular localization, suggest that the role of PRMT5 in melanoma may differ from its role in other cancers." (PMID 24098663, 2013). "Additionally, melanoma tissue displayed significantly higher cytoplasmic PRMT5+ cells as compared to normal epidermis (p<0.0001), but a lower percentage of cytoplasmic PRMT5+ cells when compared to melanocytic nevi (p<0.0144)." (PMID 24098663, 2013). "PRMT5 also did not associate with cyclin D1 in either unsynchronized melanoma cells, or cells harvested in G1 or G2/M phases following double thymidine block (not shown)." (PMID 24098663, 2013). "Importantly, since PRMT5 inhibition enhances checkpoint immunotherapy in melanoma models, combining PRMT5 inhibitors with immunotherapy may provide a treatment option for patients who fail immunotherapy alone." (PMID 41425556, 2025). "Some of the proteins (e.g., PRMT5) and miRNAs (miR-210, miR-1290) of the secreted hypoxic signature might represent promising melanoma biomarkers and interesting players involved in shaping the melanoma microenvironment." (PMID 32183388, 2020). "We hypothesized that PRMT5 plays a role in regulating the growth of human melanoma cells." (PMID 24098663, 2013). "We hypothesized that PRMT5 plays a role in regulating growth of human melanoma." (PMID 24098663, 2013).
melanoma (continued). "PRMT5 inhibitors can restore IFN and chemokine production and enhance melanoma sensitivity to immune checkpoint inhibitors." (PMID 40166469, 2025). "Then, as an essential cofactor of PRMT5, WDR77 was selected as the most prognostically significant gene, prompting comprehensive study into its role in melanoma pathogenesis." (PMID 41425556, 2025). "For instance, PRMT5, a histone methyltransferase, regulates immune-related gene expression and its inhibition enhances ICI efficacy in melanoma models." (PMID 41425556, 2025). "PRMT5 methylates IFN-γ inducible protein 16 (IFI16) and suppresses NLRC5 transcription, inhibiting the cGAS-STING and MHCI pathways in melanoma, thereby weakening IFN signaling and antitumor immune responses." (PMID 40166469, 2025). "Elevated PRMT5 (protein arginine methyltransferase 5), a component of the cGAS/STING pathway, has been correlated with prolonged survival among patients with melanoma and decreased melanoma growth in murine models." (PMID 38473384, 2024). "To investigate, we compared the gene composition of melanoma cells treated with CDK4/6 and PRMT5 inhibitors using PCA, which revealed each treatment reproducibly results in distinct expression profiles across the two cell lines." (PMID 37917641, 2023). "In this study, we used paired-end sequencing of full-length mRNA transcripts to quantify and compare the effects of CDK4/6 inhibition and PRMT5 inhibition on gene expression and alternative RNA splicing within the CHL1 and A375 melanoma cell lines." (PMID 37917641, 2023). "PRMT5 methylates IFI16/IFI204 and inhibits NLRC5 transcription, suppresses inflammation and antigen presentation, and promotes melanoma growth." (PMID 37163421, 2023). "Recently in melanoma cell lines, inhibition of CDK4/6 with palbociclib was shown to alter pre-mRNA splicing by modulating PRMT5 activity." (PMID 37917641, 2023). "In contrast, attenuating PRMT5 activity by short hairpin RNA or the small molecular inhibitor, EPZ015666 in melanoma B16 cells, increased CCL5 and CXCL10 expression after stimulation." (PMID 35493527, 2022). "We observed co-upregulation of WDR77 and PRMT5 in melanoma, suggesting that patients with high WDR77 expression may benefit from PRMT5-targeted therapies currently under clinical evaluation." (PMID 41425556, 2025). "We performed full-length mRNA sequencing on CHL1 and A375 melanoma cell lines treated with the CDK4/6 inhibitor palbociclib and the PRMT5 inhibitor GSK3326595 and analysed data for differential gene expression and differential pre-mRNA splicing induced by these agents." (PMID 37917641, 2023). "Although PRMT5 is a protein within the CDK4/6 pathway that regulates various cellular processes, how the global effects of CDK4/6 inhibition in melanoma, relate specifically to PRMT5, are currently not well understood." (PMID 37917641, 2023). "The global effects of CDK4/6i on alternative splicing in melanoma and to what extent they depend on PRMT5 are not known." (PMID 37917641, 2023). "As PRMT5 in tumor cells inhibited PD-L1 expression, GSK3326595 (PRMT5 inhibitor) and anti-PD-1 combination therapy was more effective than either treatment alone in murine xenograft liver tumors, a MYC-driven spontaneous HCC model, and murine melanoma models." (PMID 35493527, 2022). "The mechanism is that PRMT5 inhibition increases the abundance of infiltrated immune cells, but has no obvious effects on melanoma cells." (PMID 35111150, 2021). "PRMT5 depletion antagonizes melanoma growth in immunocompetent but not immunocompromised mice whereas PRMT5 overexpression accelerates tumor growth." (PMID 32743345, 2020). "Notably, cyclinD1/CDK4 also induces MEP50 phosphorylation which increases PRMT5 activity, and correspondingly, melanoma that were treated with CDK4/6 inhibitor and developed resistance also exhibited high PRMT5 activity." (PMID 32743345, 2020).